LCN2 (lipocalin 2)
Diseases named in the same sentence as LCN2 in open-access papers (continued):
Sharing a sentence is not in itself a finding about the gene and the disease.
breast carcinoma (continued). "Orthotopic implantation of LCN2-overexpressed MCF-7 breast cancer cells in mice increased local tumor invasion and growth when compared to parental MCF-7 cells." (PMID 32575507, 2020). "More importantly, LCN2 was validated to mediate the communications between tumor stroma and tumor cells, stimulating the epithelial–mesenchymal transition process in breast cancer." (PMID 32076707, 2020). "In breast cancer cell LCN2 can induce HIF1A expression, which is an important transcriptional factor mediated EDN1 gene expression in endothelial cells." (PMID 32968110, 2020). "LCN2-siRNA-based silencing in the highly aggressive and invasive breast cancer cell line MDA-MB-231 decreased cell migration and suppressed the mesenchymal phenotype." (PMID 32575507, 2020). "Other studies have validated these results by confirming LCN2’s presence in well-characterized invasive breast cancer tissues, urine of metastatic breast cancer patients, and breast cancer cell lines." (PMID 32575507, 2020). "Upregulation of LCN2 was observed in a variety of cancers, such as lung cancer, breast cancer, prostate cancer, pancreatic cancer and esophageal cancer." (PMID 33425761, 2020). "To further examine the association between LCN2 and the extent of immune infiltration in different subtypes of breast cancer, we analyzed the correlation between LCN2 and immune checkpoint gene expression." (PMID 33425761, 2020). "Overexpression of LCN2 in MCF-7 breast cancer cells, which normally express low LCN2 levels and exhibit an epithelial phenotype, induced the transition to a mesenchyme-type morphology." (PMID 32575507, 2020). "SiRNA-mediated silencing of LCN2 has been tested in breast cancer and cholangiocarcinoma (CCA) cells." (PMID 32575507, 2020). "Consistently, elevated Lcn-2 levels in the urine of breast cancer patients are correlated with a poor metastatic outcome." (PMID 30641920, 2019). "Several studies in humans suggest Lcn-2 as a pro-tumorigenic factor in breast cancer, correlating with a decreased survival and reduced responsiveness to neoadjuvant chemotherapy." (PMID 30641920, 2019). "Two reports dealing with the macrophage-epithelium iron transfer in mammary carcinoma describe a critical contribution of macrophage-secreted LCN2 to optimal proliferation and iron supply of cancer cells in vitro." (PMID 30534534, 2018). "When LCN2 was knocked down by ICAM-LCN2-LPs in breast cancer cells, VEGF and angiogenesis all reduced both in vitro and vivo." (PMID 29789480, 2018). "CHI3L1 and LCN2 have previously been identified as immune-related biomarkers for disease outcome in breast cancer patients as well as for monitoring tumor progression in the intraductal mouse model for TNBC." (PMID 30111338, 2018). "The upregulation of IFI27 was first reported in the psoriasis model, and in recent years, it has been found that IFI27, together with LCN2, can be used as two basal breast cancer subtype markers." (PMID 29580248, 2018). "Studies in humans pointed to Lcn-2 as a pro-tumorigenic factor in breast cancer, correlated with decreased survival and reduced responsiveness to neoadjuvant chemotherapy." (PMID 28979267, 2017). "To avoid the severely retarded growth effect caused by the double knockdown, we used IL-1β-neutralizing antibody to treat LCN2-depleted MDA-MB-231 breast cancer cells for evaluating the colony formation." (PMID 28281525, 2017). "Mechanistically, overexpression of Lcn-2 in non-invasive human MCF-7 breast cancer cells elicits an aggressive phenotype that promotes growth and metastasis by inducing epithelial-to-mesenchymal transition." (PMID 28979267, 2017). "The heterotypic cell-cell interaction within the breast cancer microenvironment upregulated IL-1β/LCN2 expressions in breast cancer cells, which in turn markedly enhanced breast cancer tumour progression." (PMID 28281525, 2017).
breast carcinoma (continued). "Previously, it was shown that LCN2 promotes lung metastasis of murine breast cancer cells in vitro and in vivo after injection of LCN2-overexpressing 4T1 cells with the notion that LCN2 is linked to the early events of tumor metastasis." (PMID 28804221, 2017). "The release of LCN2 from macrophages also induced an epithelial-mesenchymal transition program in MCF-7 breast cancer cells and enhanced local migration as well as invasion of tumor cells into the extracellular matrix using a three-dimensional spheroid model." (PMID 28804221, 2017). "We further obtained evidence that Lcn-2 was expressed in primary human macrophages in response to dying MCF-7 breast cancer cells." (PMID 28979267, 2017). "The correlation between MCT2 expression and poor prognosis in breast cancer was further strengthened when combined with either high expression of IL-1β or LCN2 (cut-off value of −ΔCt: −7.34 for IL-1β and −7.42 for LCN2, respectively)." (PMID 28281525, 2017). "Adding IL-1β antibody further reduced the colony number of LCN2-depleted MDA-MB-231 breast cancer cells co-cultured with MGDAs, suggesting that both IL-1β and LCN2 contribute to MGDAs-mediated tumour malignancy." (PMID 28281525, 2017). "As for breast cancer, LCN2 has been demonstrated to increase breast cancer tumorigenesis and metastasis." (PMID 27110769, 2016). "LCN2, one kind of breast cancer metastasis stimulator, was also found for the first time to be repressed by 1α,25(OH)2D3 and MART-10 in breast cancer cells." (PMID 27110769, 2016). "In breast cancer, LCN2 is stimulated by the HER2 (human epidermal growth factor receptor 2)/PI3K (phosphoinositide 3-kinase)/AKT pathway." (PMID 26840566, 2016). "On one hand, LCN2 expression provokes tumor growth and progress in breast cancer and increases the migration/invasion of pancreatic cancer." (PMID 27912767, 2016). "There are several other biomolecules and pathways known to contribute to the expression of LCN2 in inflammatory cells, macrophage cell lines, epithelial cells, breast cancer cell lines, and hepatocytes." (PMID 27729871, 2016). "Overexpression of LCN2 in MCF7 breast cancer cells increases the expression of vascular endothelial growth factor (VEGF), a key angiogenic activator." (PMID 25476483, 2015). "LCN2 has been shown to suppress apoptosis in thyroid, lung, and breast cancers, thus we wanted to ascertain if LCN2 promoted survival in PDAC." (PMID 23056397, 2012). "LCN2 has been described to be a potential biomarker for cancer progression as it has been found in the urine of breast cancer patients and in the serum of PDAC patients." (PMID 23056397, 2012). "Our study suggests that the elevated levels of lipocalin-2 and MMP-9 are associated with reduced breast cancer survival, particularly in patients with lower BMI and lymph-node negative breast cancers." (PMID 22640376, 2012). "In the present study, we examined the association between preoperative serum levels of lipocalin-2 and MMP-9 and disease-free survival (DFS) and determined the potential of both proteins as noninvasive biomarkers in predicting the recurrence of breast cancer." (PMID 22640376, 2012). "Approximately 50% of the tumors in the present study were positive for LCN2 expression, comparable to breast cancers with staining in 33% of the cases." (PMID 22559235, 2012). "The proposed mechanisms by which lipocalin-2 promotes growth and metastasis of breast cancer cells are multiple." (PMID 22737251, 2012). "Elevated lipocalin-2 and MMP-9 levels were associated with reduced DFS of breast cancer ( Ptrend = 0.029 and Ptrend = 0.063, respectively)." (PMID 22640376, 2012). "Further, E-cadherin expression was down-regulated in breast cancer cell lines overexpressing LCN2, and tumor cells showed an increased motility and invasiveness accompanied by upregulation of mesenchymal markers." (PMID 22559235, 2012).
breast carcinoma (continued). "In order to directly address the role of lipocalin-2 in development of breast cancer, we initiated a study examining the role of lipocalin-2 in the spontaneous mouse mammary tumor virus-polyoma middle T antigen (MMTV-PyMT) mouse model." (PMID 22737251, 2012). "Our investigation therefore leads us to conclude that the role of lipocalin-2 in breast cancer progression is questionable." (PMID 22737251, 2012). "In comparison, increased LCN2 promotes breast cancer progression and metastasis by facilitating epithelial-to-mesenchymal transition." (PMID 23236365, 2012). "Similar findings have been found in several breast cancer studies that have demonstrated the critical role of LCN2 expression in the aggressive growth of tumours and the dissemination of metastases." (PMID 23056397, 2012). "This is in contrast to two recent reports using much the same approach as here to study the role of lipocalin-2 in breast cancer development." (PMID 22737251, 2012). "Depletion of LCN2 in colon, gastric, and breast cancer models diminishes MMP-9 activity thereby attenuating invasion." (PMID 23056397, 2012). "Both previous reports on spontaneous transgenic breast cancer in a lipocalin-2 knock-out or wild-type background have identified a high-molecular weight form of MMP-9." (PMID 22737251, 2012). "In a mouse model of breast cancer, LCN2 protein expression increased during tumor progression and returned to normal following regression." (PMID 22559235, 2012). "The mice used for examining the effect of ErbB2-induced mammary tumors was obtained by breeding Lcn2−/− (C57BL/6) mice with MMTV-ErbB2 (FVB/N) mice." (PMID 22737251, 2012). "Another explanation would be that the expression of lipocalin-2 in mammary tumors is significantly lower in our study than the expression in the mammary tumors in the two other reports." (PMID 22737251, 2012). "We confirmed that cancer cells of diverse histological origin, including murine melanoma and lung carcinoma, and human colon, ovarian, and breast carcinoma, upregulate LCN2 transcription under ER stress." (PMID 21649922, 2011). "For example, lipocalin 2 (Lcn2), a small extracellular protein involved in iron transport, has been shown to promote breast cancer progression and metastasis and is found in urine of patients with metastatic breast cancer." (PMID 21589862, 2011). "For instance, Lipocalin 2 is upregulated in human cancers of several origins and, importantly, its levels correlate with the aggressiveness of clonally-derived murine breast cancer cell lines." (PMID 21649922, 2011). "It is believed that LCN2 promotes breast cancer progression by inducing epithelial to mesenchymal transition (EMT) and by increasing cell motility and invasiveness through down-regulation of E-cadherin." (PMID 20078854, 2010). "Under normal conditions, expression of lipocalin 2 is restricted to breast; however, increased lipocalin 2 levels have been reported in breast cancer." (PMID 19077278, 2008). "The effects of lipocalin 2 overexpression on the malignancy of breast cancer cells were examined using cell proliferation assay, migration assay, invasion assay, and soft agar assay in vitro." (PMID 19077278, 2008). "In this study, we overexpressed lipocalin 2 in 4T1 mouse mammary tumor cells, and investigated the effects and molecular mechanisms of lipocalin 2 on breast tumor malignant properties." (PMID 19077278, 2008). "IBCs are more commonly HER2+ or TNBC compared with non-IBCs, and interestingly, high levels of LCN2 have been associated with these breast cancer molecular subtypes." (PMID 40732340, 2025). "Overexpression of LCN2 in breast cancer, accompanied by increased expression of the key EMT transcription factor Slug, upregulated the mesenchymal markers vimentin and fibronectin while downregulated the epithelial marker E-cadherin, increasing the invasiveness of the tumor." (PMID 40109857, 2025). "LCN2 is a mediator of EMT that promotes breast cancer metastasis." (PMID 40109857, 2025).
breast carcinoma (continued). "LCN2 may also play an important role in the progression of diseases such as Parkinson’s, breast cancer, and disc degeneration by regulating cellular senescence." (PMID 41562054, 2025). "A recent study revealed that LCN2 also plays a role in promoting breast cancer brain metastasis." (PMID 40732340, 2025). "LCN2 acts as an oncogene that promotes the progression of breast cancer as well as, oral squamous cell carcinoma, myeloproliferative neoplasm, skin squamous cell carcinoma, gastric carcinoma, esophageal squamous cell carcinoma, thyroid cancer, and prostate cancer." (PMID 40109857, 2025). "Overexpression of LCN2 has been associated with increased cancer cell motility, epithelial-to-mesenchymal transition (EMT), proliferation, angiogenesis, invasion, and metastasis in aggressive cancers, including pancreatic, esophageal, and breast cancer." (PMID 40732340, 2025). "When HIC1 expression is restored in breast cancer, elevated levels of LCN2 are antagonized by HIC1." (PMID 40109857, 2025). "For instance, an Anti-CXCR4- targeted liposome encapsulating LCN2 siRNA effectively targets metastatic breast cancer cells and significantly blocks migration in triple-negative human breast cancer cells (88% for MDA-MB-436 and 92% for MDA-MB-231) along the CXCR4-CXCL12 axis." (PMID 39188682, 2024). "Therapies capable of reducing LCN2 secretion could offer significant benefits for patients with breast cancer that has metastasized to the brain." (PMID 39188682, 2024). "LCN2 also acts as a signaling molecule that transmits signals from the periphery to the brain, promoting neuroinflammation through astrocyte activation during breast cancer brain metastasis." (PMID 39188682, 2024). "Recent studies suggested that LCN2 could be a priority target in breast cancer and other aggressive tumors, but little is known regarding the prognostic role of LCN2 in CC." (PMID 38541074, 2024). "These in vivo data confirm the previous in vitro observations that RGS10 deficiency promotes invasion and metastasis by activating the LCN2 pathway to induce EMT in breast cancer cells, and demonstrate that RGS10 has utility as a prognostic biomarker in breast cancer." (PMID 39145770, 2024). "Furthermore, LCN2 released by N2-neutrophils also promotes the mesenchymal-epithelial transition (MET) of breast cancer cells during metastasis via ERK/KLF4 signaling, thereby facilitating colonization and metastatic outgrowth." (PMID 39188682, 2024). "In primary tumors, LCN2 promotes the proliferation and angiogenesis of breast cancer cells, triggers the epithelial-mesenchymal transition, interacts with matrix metalloproteinase-9, thereby facilitating the reorganization of the extracellular matrix and enhancing cancer cell invasion and migration." (PMID 39188682, 2024). "Notably, intracellular expression of LCN2 has been shown to promote the progression of various tumors, such as breast cancer, colorectal cancer, cholangiocarcinoma." (PMID 39188682, 2024). "This leads to the suggestion that LCN2 could be a potential target for therapeutic interventions aimed at inhibiting the progression of breast cancer." (PMID 39150915, 2024). "Second, the mechanism by which the MIR539-5p/RGS10/LCN2 axis may be related to outcomes in patients with breast cancer remains to be elucidated." (PMID 39145770, 2024). "Moreover, in both cholangiocarcinoma (CCA) and breast cancer cells, the siRNA technology to silence Lcn-2 was tested, whereby in the former study, the knock-down of Lcn-2 in the cholangiocarcinoma cell line RMCCA-1 reduced its metastatic properties in vitro." (PMID 37958332, 2023). "In some types of cancer (especially breast cancer), the development of therapeutic agents targeting LCN2 may have major clinical implications for the treatment of metastasis." (PMID 36926025, 2023). "Targeting Lcn-2-related pathways focuses mainly on breast carcinoma studies." (PMID 37958332, 2023).
breast carcinoma (continued). "Indeed, the overexpression of C/EBP ζ in MDA-MB-231 cells resulted in decreased MMP9 and Lcn-2 expression, coinciding with the inhibition of the migration and invasion of breast cancer." (PMID 37958332, 2023). "Additionally, the inactivation of Lcn-2 by CRISPR/Cas9 gene deletion increases the response to chemotherapy in murine breast cancer." (PMID 37958332, 2023). "Finally, BMP2, a known protumorigenic ligand in breast cancer, impressively suppressed LCN2 mRNA and protein levels in doxorubicin-resistant 4T1 cells." (PMID 36077676, 2022). "Higher serum levels of LCN2 were observed in breast cancer patients compared to healthy women." (PMID 35818030, 2022). "Similar to breast cancer, we speculate that estrogen receptor alpha (ERα) might also be related to LCN2 in PCa." (PMID 35053376, 2022). "In breast cancer, increased LCN2 levels promote cancer cell proliferation and angiogenesis." (PMID 35989326, 2022). "Hence, silencing Lcn2 in breast cancer cells can help to reduce metastatic breast cancer and triple-negative breast cancer progression." (PMID 33916786, 2021). "Interestingly, recent studies of leptomeningeal metastasis have shown that similar to breast cancer cells, these cancer cells utilize Lcn2 to obtain iron from macrophages in the CNS space which promotes tumor growth." (PMID 33986740, 2021). "Lipocalin 2 (LCN2), also known as neutrophil gelatinase associated lipocalin (NGAL), regulates angiogenesis and has been reported to be elevated in several types of cancer, including breast cancer." (PMID 34299272, 2021). "Thus, given the importance of iron-export and iron-transporting proteins such as FPN and Lcn-2 in the tumor context, we aimed at clarifying their role and/or interplay in breast cancer." (PMID 33808732, 2021). "Heterogeneous expression of LCN2 was reported in patients with primary breast cancer." (PMID 34072157, 2021). "Interestingly, primary tumor expressing ANGPTL7, MMP3, LCN2, S100A8, and ESM-1 levels that were upregulated in 4T1.2 cells was strongly associated with breast cancer patients’ survival outcomes." (PMID 34072157, 2021). "LCN2 expression is higher in solid tumors than in corresponding normal tissues, and it is mainly described as tumor promoter in many cancers, including pancreas, glioblastoma, thyroid, kidney, esophagus, and breast cancer." (PMID 34342930, 2021). "In conclusion, we show that stromal/TAM-derived iron-bound Lcn-2 was linked with breast cancer progression, independent of the expression of the iron exporter FPN." (PMID 33808732, 2021). "To establish clinical relevance, we investigated further using larger cohorts SCAN-B and METABRIC of breast cancer patients data analysis suggested that LCN2 expression score is high in aggressive breast cancer HER2+ or TNBC, but not linked with any survival outcome of these subtypes." (PMID 34072157, 2021). "Urine of breast cancer patients demonstrates elevated Lcn2 levels." (PMID 33916786, 2021). "Lcn2 can induce EMT in breast cancer through estrogen receptor α/Slug axis." (PMID 33916786, 2021). "Moreover, we showed that TAM release iron, bound to the iron-transporting protein lipocalin-2, which, in turn, promoted tumor growth in an experimental mammary tumor model." (PMID 34069743, 2021). "For example, in breast cancer, increased LCN2 levels promoted cell proliferation and angiogenesis." (PMID 32575507, 2020). "Furthermore, adipocyte- or CAA-secreted factors, including leptin, TNF-α, IL-6, IL-1β, IGFBP-2, LCN2, collagen VI, and others, have also been demonstrated to promote breast cancer cell malignant progression, such as EMT, invasion, and metastasis." (PMID 32242230, 2020). "Moreover, cytokines, such as IL-17 and TNF-a, activate transcription of LCN2, and stroma-derived LCN2 enhances the malignant phenotype of breast cancer cells and promotes cell metastasis, possibly by interacting with MMP-9." (PMID 32575507, 2020).